AR (androgen receptor)
Diseases named in the same sentence as AR in open-access papers (continued):
Sharing a sentence is not in itself a finding about the gene and the disease.
tumor (continued). "Notably, the isolated circulating tumor cells (CTC) from mCRPC patients with abiraterone- or Enz-resistance showed gene amplification of AR (AR gain) in 50% of patients." (PMID 33810413, 2021). "We hypothesized that AR activity within the tumor has clinical implications and investigated whether androgen responsive serum factors might serve as a minimally invasive indicator of tumor AR activity." (PMID 34736512, 2021). "Interestingly, depending on which different signalling pathways are activated, AR can promote or suppress proliferation and apoptosis in tumours." (PMID 34283051, 2021). "New evidence on indirect paracrine regulation of the prostate epithelial cells through AR signaling in the stroma challenges the current practice of indiscriminate androgen ablation therapy and harbingers a need for therapies selectively targeting AR’s in the tumor stroma." (PMID 33668112, 2021). "Furthermore, DKK-1 expression in tumor cells activated Wnt/β-catenin signaling and demonstrated an interaction with AR signaling." (PMID 34357036, 2021). "The quantification of AR signaling in tumor samples of 30 SDC patients using a composite metric summarizing expression levels of AR target genes in a score called the AR pathway score was found to be predictive for clinical benefit (complete or partial response or stable disease >6 months)." (PMID 34298742, 2021). "This suggests that AR signaling increases tumorigenesis and tumor cell survival." (PMID 34768683, 2021). "In PCa, the functional synergy between the AR and NF-κB has the potential to increase the chemoresistance to antiandrogens that could promote aggressive tumor growth." (PMID 33803759, 2021). "Moreover, we have also proved the role of AR in the formation of VM in vivo via the orthotopic implantation model, finding increased VM formation, increased tumor progression, and more metastases in xenografts established by cells with AR overexpression." (PMID 33510354, 2021). "However, in the last decade, second-generation androgen-receptor (AR) signaling inhibitors (i.e., enzalutamide) and intra-tumor androgen synthesis inhibitors (i.e., abiraterone) have been approved for the treatment of mCRPC with improved survival benefits." (PMID 34386430, 2021). "They showed that high levels of the inflammatory cytokine Il-23 mediated paracrine effects on tumor-infiltrating MDSCs by activating downstream androgen receptor (AR) target genes through the signal transducer and activator of transcription 3 (STAT3)–RORγ signaling axis in tumor cells." (PMID 34502458, 2021). "The androgen receptor is expressed during tumor initiation and progression." (PMID 34204596, 2021). "These hub biomolecules of tumor stroma network, AR, GATA2, miR-124, TOR1AIP1, ESR1, EGFR, STAT1, miR-192, GATA3, COL1A1, may give crucial information about tumorigenesis." (PMID 33907495, 2021). "Nevertheless, AR signalling is mainly considered oncogenic in these tumour settings." (PMID 35008851, 2021). "AVR-110 also reduced AR-target gene expression in enzalutamide-resistant tumor models, targeted wild type AR (WT-AR), and amplified AR with T878A, H875Y, F877L, and M895V mutations, but not in tumors with L702H or AR-V7 mutations." (PMID 34771580, 2021). "In practice, biomarkers including tumor molecular sequencing, circulating tumor DNA, circulating tumor cell enumeration and androgen receptor characteristics, and tumor cell surface expression (PSMA), all may have a role in therapy selection." (PMID 34830878, 2021). "Consequently, overstimulation of the AR signalling axis can trigger uncontrolled cell growth enabling oncogenic transformation and tumour growth, therefore making the AR a major therapeutic target." (PMID 33993099, 2021). "We identified multiple primary PCa genomic subtypes, and given their differing effects on AR activity, patient tumor genetics may be an important stratifying factor for AR therapy resistance." (PMID 34208794, 2021).
tumor (continued). "There was no statistical evidence that tumor size, regional lymph node involvement, or the presence of distant metastasis had an association with AR gene expression levels." (PMID 34571711, 2021). "To assess AR protein expression and localization, we performed IHC analysis on tumour sections from the MIBC (T3) specimen with the highest AR mRNA expression from our microarray cohort, using the AR N and C terminus‐specific antibodies, N20 and Ep670Y, respectively." (PMID 33797847, 2021). "As per TNBCtype, 56% of the tumours in Cluster s5 were of the luminal androgen receptor subtype." (PMID 33673506, 2021). "Paradoxically, a higher expression of AR is associated with better prognosis based on a retrospective analysis from the TCGA database, indicating that AR function in ccRCC is complex and may be tumor stage-dependent." (PMID 33510354, 2021). "We are therefore working to add AMACR and p63 to our flow cytometry panel and are also planning to include global genomic and transcriptomic analyses of our PDCOs to evaluate for tumor-specific molecular alterations such as ERG, AR splice-variants, and NEPC markers." (PMID 34581895, 2021). "AR levels in tumours from 14 patients were measured by immunohistochemistry (IHC; left)." (PMID 34382934, 2021). "Similarly, PC3 overexpressing AR under a natural AR promoter suppresses tumor growth, metastasis formation, and cell invasion both in vitro and in vivo." (PMID 33420371, 2021). "SPOP has been shown to participate in diverse cellular processes and plays tumor suppressive and oncogenic roles in PrCa by targeting different substrates for ubiqutination-mediated proteolysis, including AR, steroid receptor coactivator 3 (SRC-3), DEK, TRIM24, BRD4 and Nanog." (PMID 34857003, 2021). "Most studies report either 1% or 10% of AR-positive cells present in a tumor sample as positive." (PMID 33915941, 2021). "The results were interpreted as: although all Nanog+ cells were also AR+ and Nanog protein staining heavily co-localized with AR protein, AR expression was much more diffusely seen in tumor cells than Nanog due to the findings that many weakly AR+ cells were Nanog negative." (PMID 34094902, 2021). "AR signaling abrogation has been responsible for tumor growth and metastasis." (PMID 33499881, 2021). "An important question that arises is whether the link between ATF6 and AR exists in PCa patients after androgen deprivation therapy, given that their tumor still abundantly express AR." (PMID 34521429, 2021). "Pharmacological inhibition (with ABC294640) of sphingosine kinase 2 (SphK2), one of the two Sphk isoforms that catalyzes the synthesis of S1P from sphingosine, effectively reduced CRPC cell proliferation and xenograft tumor growth by targeting AR and the oncogene MYC." (PMID 34386430, 2021). "In addition, we show that the bromodomain histone reader ZMYND11 is a SPOP substrate implicated downstream of SPOP in the opposing regulation of the ERG and AR pathway in the two tumor subtypes." (PMID 33531470, 2021). "Tumor hypoxia is associated with progression to CRPC, AR signaling, and treatment resistance." (PMID 33671134, 2021). "Based on the incompatibility between the two tumor subtypes, our work enabled the development of specific custom signatures related to AR and ERG transcript that are necessary to drive proliferation and tumorigenesis in the context of ERG-positive and SPOP-mutants tumors." (PMID 33531470, 2021). "The obvious gender advantage of HCC indicates that androgen receptor (AR) may play an important role in the tumor occurrence, develop and metastasis of HCC." (PMID 33753989, 2021). "In contrast, NEPC is characterized by low expression of AR and could be developed from AR-positive tumor via lineage plasticity induced by increased expression of other TFs, such as N-MYC13, SOX214, and ONECUT215,16." (PMID 34145268, 2021). "This indicates that AR also has tumour suppressive activity." (PMID 34685579, 2021).
tumor (continued). "In other words, the prolonged therapeutic use of AR‐antagonists as a selective pressure could induce tumor subclones with higher malignancy, especially in the case of mCRPC." (PMID 34318630, 2021). "High expression of p-mTOR may drive tumor proliferation in almost one third of TNBC, and the p-mTOR positivity is associated with AR expression." (PMID 33915941, 2021). "AR antagonists may activate the immune system (inducing tumor cell apoptosis, thymic enlargement, and leukocytes/B cell migration), and they could exert immunosuppressive effects through an AR-independent pathway." (PMID 34830179, 2021). "Besides AR pathway activity, six other potential tumor-driving pathways were analyzed: Notch, MAPK, TGFβ, ER, HH, and PI3K." (PMID 34298742, 2021). "On the other hand, AR in tumor cells may be up or down regulated and each AR type may have opposite roles, thus raising doubts on the best way to attack a given cancer." (PMID 34831054, 2021). "The results revealed that shAR could promote the tumor progression in the mouse model, and oemiR-122-5p could partly reverse AR’s function in the mouse tumor model." (PMID 34745992, 2021). "Given the critical role of AR in PCa progression and treatment resistance, any changes to the transcriptional landscape could alter tumor cell proliferation and sensitivity to AR pathway inhibitors." (PMID 33975627, 2021). "Interestingly, a female patient diagnosed with a strong AR-expressing tumor showed complete remission upon treatment, but all patients received parallel chemotherapy impairing a direct drug-effect correlation." (PMID 34768978, 2021). "Based on these data, we further hypothesized that the ING1 and ING2 tumor suppressors are involved in the AR-mediated transrepression of hTERT." (PMID 34439179, 2021). "Forty-three out of 58 GBM patients (74%) examined so far in our database display positive AR expression in >10% tumor cell nuclei, with the other eleven patients showing 1–10% positivity (93% with >1% positivity) and only four patients’ tumor were found to be completely devoid of AR staining." (PMID 34094902, 2021). "Our results from confocal microscopy also confirmed that AR expression can be detected in both CD133+ and CD133− tumor cells although AR expression levels, as indicated by staining intensity, were shown to be highest in isolated CD133+ cells than clustered CD133+ cells and AR+/CD133− cell." (PMID 34094902, 2021). "In 19/20 tumours, AR stained more than 95% of the neoplastic cells." (PMID 33534004, 2021). "Moreover, expression of FGFR1 is associated with transition to CRPC, and the FGF pathway can drive tumor progression in tumors refractory to AR-directed therapies." (PMID 33471819, 2021). "Finally, androgens regulated the expression of nearly 300 genes, some of which correlated with AR expression in UCC tumour tissues." (PMID 33797847, 2021). "We hypothesised that ablation of AR expression would be the most appropriate ‘therapeutic benchmark’ to identify the key regulators of tumour cell survival regulated by AR." (PMID 34382934, 2021). "In contrast, AR in PCa epithelium acted as a tumor-promoting factor to control PCa development." (PMID 34692685, 2021). "In line with this, SAL represses hTERT expression, the catalytical subunit of the telomerase, which might be a factor as a tumor-suppressive function of AR." (PMID 34439179, 2021). "By interrupting the downstream effects on tumor cell proliferation and growth via enhanced PSMA expression, this treatment combination interferes with the accumulation of gain-of-function point mutations in the AR gene and mismatch repair." (PMID 34298770, 2021). "Therefore, the combined PI3K/AKT inhibition and AR signaling results in almost complete tumor regression, prolonged tumor growth inhibition, and PSA stabilization in a preclinical CRPC model." (PMID 33921329, 2021). "Assessments of tumor AR signaling by liquid biopsy have been reported by other groups." (PMID 34736512, 2021).
tumor (continued). "Apart from the removal of the tumour suppressive function, PTEN loss has also been associated with AR signalling suppression and inhibition of androgenic genes; this may drive PC into an androgen-independent phenotype, ultimately reducing the efficacy of ADT." (PMID 34357131, 2021). "However, there were clear exceptions to this general conclusion as evidenced by the juxtaposition of AR+/NE− and AR−/NE+ tumor phenotypes within the same metastasis." (PMID 33658518, 2021). "It was demonstrated to play a key role in AR-mediated tumor growth and progression in CRPC cells." (PMID 34067217, 2021). "Consistently, ChoKa inhibition decreased AR protein levels and AR transcriptional program, and inhibited the growth of PCa cell lines, human PCa explants, and tumor xenografts, suggesting ChoKa as a marker of tumor progression and a potential therapeutic target." (PMID 34386430, 2021). "Initial evidence suggests that tumour cells with low AR signalling dependence may be inherently resistant, while cells lacking the machinery required for an adaptive acute stress response are intrinsically sensitive." (PMID 35008330, 2021). "It was observed that during tumor progression, a change of AR expression is present." (PMID 33915941, 2021). "Notably, CRPC remains largely AR-dependent due to aberrant reactivation of AR through multiple distinct mechanisms that promote AR-mediated cell proliferation, DNA repair, and tumor survival." (PMID 33452241, 2021). "Fluctuations in hormone levels may induce inflammation within tumor microenvironments and increase both NF-κB and AR function, the extent of which can be potently regulated by nuclear Nrf2 levels." (PMID 35582006, 2021). "Therefore, mirroring AR, the tumour suppressor vs. oncogenic potential of GR is dependent upon ER expression." (PMID 34638457, 2021). "In addition, silencing the expression of AR in PCa cells by RNA interference, it was found that AR knockdown resulted in more powerful STAT3 activation, thereby compensating for the silenced AR and promoting tumor growth." (PMID 33995485, 2021). "MDSCs secrete IL-23 and may activate AR signaling at least in a subset of castration-resistant PCs, representing an important component of the tumor immunosuppressive microenvironment." (PMID 34830196, 2021). "In addition, PTEN loss, which is one of the most frequent alterations found in PCa, can promote tumor growth independently from AR signaling." (PMID 34069147, 2021). "In clinical practice, pathological examination including estimation of tumor-infiltrating lymphocytes (TILs) or immunohistochemistry for AR, gross cystic disease fluid protein 15 (GCDFP-15), EGFR, CK5/6, E-cadherin, or PD-L1 is expected as a substitute for molecular analysis." (PMID 34070471, 2021). "Immunofluorescence and immunohistochemistry reactions showed that steroid sulfatase (STS) was located in the cytoplasm of epithelial tumor cells displaying a distribution similar to cytokeratins, whereas the androgen receptor (AR) was identified in the nucleus of tumor epithelium." (PMID 34321053, 2021). "Similarly, miR-30 directly inhibits the AR expression and miR-30, enhancing the AR expression and androgen-independent cell growth, ultimately acting as a tumor suppressor in PC." (PMID 33499881, 2021). "In our study, we found that decreased AR expression could increase the migration and invasion capacities in HCC cells, which was another study to prove AR seems to be a tumor suppressor for HCC in late stage." (PMID 33753989, 2021). "The tumor was also positive for androgen receptor (AR, 30%)." (PMID 33772089, 2021). "Although a high expression level of AR has been associated with increased survival of ER+ BCa patients, the Richer group found that inhibition of AR by enzalutamide (ENZ) (a second generation antiandrogen) decreased BCa cell proliferation and tumor size." (PMID 34137734, 2021).
tumor (continued). "A large multi-institutional study including about 1,407 TNBC tumours issued after this meta-analysis concluded that the AR-positivity was a marker of good prognosis in USA and Nigerian cohorts, whereas it conferred poor prognosis in Norway, Ireland and Indian cohorts, and was neutral in UK cohort." (PMID 35047068, 2021). "Interestingly, allografts from either genotype contained tumor cells that were either AR-negative, weak, or strong, indicating that organoids that were initially AR-positive in vitro gradually lost AR expression in vivo." (PMID 34099734, 2021). "Furthermore, ChIP-seq showed that deleting CHD1 re-organized the AR cistrome to an AR cistrome mimicking that of an oncogenic PCa phenotype, thus driving tumor growth in murine models of PCa through TFs such as HOXB13, BRN2, and GR." (PMID 33525365, 2021). "At the same time, JAK/STAT and AR pathways have synergistic functions in tumor cells, which may be related to the progression of PC." (PMID 34215720, 2021). "AR pathway reactivation after ADT is an important process that leads to tumor progression." (PMID 33974560, 2021). "Consequently, TRIM28 knockdown decreased colony formation of AR-dependent PC cells and diminished xenograft tumor development." (PMID 34208621, 2021). "Importantly, AKT signaling is enhanced under the conditions of an androgen receptor (AR) blockade, driving the resistance to the anti-androgen therapy and enabling the tumor to circumvent the need for androgens to promote tumor cell growth and survival." (PMID 35366279, 2021). "Lung and liver metastatic lesions were AR negative, however, lymph node metastatic lesions contained both AR-positive and negative tumor cells, suggesting that loss of AR expression is not necessary for metastasis." (PMID 34099734, 2021). "A recent study showed that patients with nuclear-localized AR-V7 protein in circulating tumor cells might have longer survival if treated with taxane chemotherapy than AR signaling inhibitors." (PMID 35115934, 2021). "However, it is worth underlining that, in these patients, the disease is rare and only documented by a few case reports evaluating AR expression in tumour tissue." (PMID 35008851, 2021). "These inhibitors effectively block AR and ER activity and tumor growth." (PMID 34201346, 2021). "Altogether, these results suggest the effect of AR as a tumor promoting factor in ER+ BC cells." (PMID 32344660, 2020). "Furthermore, the presence of AR-V7 mRNA in circulating tumor cells of patients with metastatic CRPC has been shown to predict poor response to AR antagonists." (PMID 32731472, 2020). "However, the tumor reappears in a more aggressive form due to the activation of alternate cellular pathways which directly or indirectly activate the AR and promote cell proliferation." (PMID 32881870, 2020). "Furthermore, the study also uncovered a significant correlation between PD-L1 overexpression and the clinicopathological features of CRPC: advanced tumor stage, higher Gleason score, positive surgical margin and positive AR status." (PMID 33318295, 2020). "By multivariate survival analysis, Sox2 was associated with poor cancer-specific survival (Hazard Ratio = 1.48, 95% confidence interval 1.04–2.11, p = 0.0292), independently of the pathologic tumor size, pathologic nodal stage, distant metastasis, and AR expression." (PMID 33553286, 2020). "Interestingly, we observed AR amplification in circulating tumor DNA (ctDNA) co-occurring with CTC-AR-V7 expression in two of five patients." (PMID 32796730, 2020). "Furthermore, concomitant treatment with abiraterone and lapatinib in CRPC cell lines blocks AR reactivation and suppresses tumour progression." (PMID 35582226, 2020). "The overall expression of AR was less across all tumour subgroups in the study population." (PMID 32928183, 2020). "We hypothesized that responses to HDT might impact the genomic expression of AR alterations found in circulating-tumor DNA (ctDNA)." (PMID 32002120, 2020).